MIR23A (microRNA 23a)
Synonyms: hsa-mir-23a; MIRN23A; miRNA23A; mir-23a
Gene: MicroRNA gene on chromosome 19 (13,836,587 to 13,836,659, reverse strand). Ensembl gene ENSG00000207980.
Gene Ontology:
Biological process: miRNA-mediated post-transcriptional gene silencing
Cellular component: RISC complex
Homologues: Orthologues: chimpanzee ptr-mir-23a (100% identical), macaque mml-mir-23a (100% identical), dog MIR23A (95% identical), pig ssc-mir-23a (93% identical), guinea pig MIR23A (92% identical), mouse Mir23a (92% identical), tropical clawed frog xtr-mir-23a-1 (75% identical), zebrafish mir23a-1 (67% identical), zebrafish mir23a-3 (64% identical), zebrafish mir23a-2 (62% identical). Paralogues in human: MIR23B (67% identical).
Diseases named in the same sentence as MIR23A in open-access papers:
MIR23A is named in the same sentence as 9 diseases in open-access papers, as found by Europe PMC text mining. Sharing a sentence is not in itself a finding about the gene and the disease. The quoted sentences say what the papers report.
kidney cancer (1 paper, 2009). Primary or metastatic malignant neoplasm involving the kidney. "In particular, CUL3, over expressed in kidney and prostate cancers, is a target of several dysregulated MIRs: MIR22, MIR23A, MIR23B, MIR218-1, MIR218-2, and MIR301, which are down regulated in kidney cancers, and of MIR22, MIR23A, MIR181A, and MIR181C, which are down regulated in prostate cancers." (PMID 19402918, 2009).
osteopetrosis (1 paper, 2023). Osteopetrosis, also known as marble bone disease, is a descriptive term that refers to a group of rare, heritable disorders of the skeleton characterized by increased bone density on radiographs. "Furthermore, MIR23a upregulation has been detected in osteopetrosis patients." (PMID 36752600, 2023).
osteoporosis (1 paper, 2023). A condition of reduced bone mass, with decreased cortical thickness and a decrease in the number and size of the trabeculae of cancellous bone (but normal chemical composition), resulting in increased fracture incidence. "Therefore, the association of osteoporosis with both upregulation and downregulation is possibly mediated through distinct mechanisms underlying the regulatory process of the Mir23a cluster." (PMID 36752600, 2023).
MIR23A also shares sentences with these, for which no sentence is quoted: acute myeloid leukemia (1 paper); hematological malignancies (1); immune deficiencies (1); infection (1); prostate carcinoma (1); viral infection (1).